MYCN (MYCN proto-oncogene, bHLH transcription factor)
Diseases named in the same sentence as MYCN in open-access papers (continued):
Sharing a sentence is not in itself a finding about the gene and the disease.
neuroblastoma (continued). "Interestingly, HDAC5 was also shown to interact with N-myc protooncogene protein (MYCN), and the complex colocalized to the CD9 promoter and attenuated CD9 expression in neuroblastoma cells, leading to tumor cell invasion and metastasis." (PMID 34178647, 2021). "MYCN non-amplified younger neuroblastoma patients with higher DST expression levels had the best clinical overall survival." (PMID 34116676, 2021). "To study the relevance of fatty acid synthesis for neuroblastoma biology, we inhibited this process with the use of five small molecule inhibitors in a panel of MYCN-amplified (MNA) and non-MYCN-amplified (NMNA) neuroblastoma cells." (PMID 33659885, 2021). "Lastly, while the negative relationship between MYCN amplifications and immune infiltration is clear, the role of additional commonly altered chromosomal alterations in neuroblastoma and immune cell infiltration is unclear." (PMID 34458583, 2021). "If changes in ECM stiffness influences differentiation, MYCN expression, and YAP expression, then the use of therapies focused on remodeling the ECM may have therapeutic gain in neuroblastoma." (PMID 34572875, 2021). "Thus, USP5 acts as an oncogenic cofactor with MYCN in neuroblastoma and the novel combination of HDAC inhibitor with SE486-11 represents a novel therapeutic approach for the treatment of MYCN-driven neuroblastoma." (PMID 33658627, 2021). "Thus, neuroblastoma cases in the ADRN-cluster were classified into two genetically distinct clusters, MYCN- and ATRX-clusters." (PMID 33465163, 2021). "No drugs currently exist that can inhibit MYCN, either directly or indirectly, for the treatment of neuroblastoma, in spite of its prognostic importance." (PMID 34069817, 2021). "This strongly argues, that elevated MYCN expression in MNA neuroblastoma is not substantially supported by the downregulation of major MYCN-regulatory miRNAs, as previously proposed." (PMID 34026620, 2021). "The MYC-driven neuroblastoma group includes both MYCN-amplified and non-amplified tumors with high MYCN and MYC expression, respectively, and they are among the worst tumors that ultimately kill the patients." (PMID 33968044, 2021). "Here, we observed an identical phenotype in yet another neuroblastoma cell line: MYCN-nonamplified SH-SY5Y." (PMID 35008802, 2021). "A recent study analyzed the consequences of MYCN over-expression or withdrawal in neuroblastoma cells at the genome-wide level using the well-characterized tet-off MYCN SHEP-21N cell line model and, additionally, a tet-on MYCN model in the parental SH-EP neuroblastoma cell line." (PMID 34200747, 2021). "We tested YKL-5-124 in MYCN-amplified and nonamplified neuroblastoma cells individually and in combination with other inhibitors in cell line and animal models." (PMID 35198433, 2021). "Genes differentially expressed in MYCN non-amplified younger neuroblastoma patients were identified using Therapeutically Applicable Research to Generate Effective Treatments (TARGET) and Gene Expression Omnibus (GEO) datasets." (PMID 34116676, 2021). "In agreement with MYC-independent mechanisms of BET inhibition that take place in some tumor contexts, ectopic overexpression of MYC/MYCN is not able to abrogate the suppressive activity of BETi in neuroblastoma and glioblastoma lines." (PMID 33668642, 2021). "MYCN gene amplification is the most recurrent form of activation of a MYC family gene in neuroblastoma, but it is not the only mechanism." (PMID 34669465, 2021). "Compared with MYCN amplified neuroblastoma patients and MYCN non-amplified older neuroblastoma patients, 64 genes were highly expressed in MYCN non-amplified younger neuroblastoma patients in TARGET dataset." (PMID 34116676, 2021). "There were 2952 and 612 genes were differentially expressed in MYCN non-amplified younger neuroblastoma patients in GSE49710 and GSE85047 datasets, respectively." (PMID 34116676, 2021).
neuroblastoma (continued). "High ALYREF expression in neuroblastoma tumor tissue had prognostic significance, which was independent of MYCN-amplification, therefore we argue that ALYREF may have MYCN-independent oncogenic effects." (PMID 33767157, 2021). "Based on their expression levels in MYCN non-amplified neuroblastoma patients, we found those genes were highly correlated with each other, as demonstrated the high correlation coefficients of those genes in TARGET, GSE49710 and GSE85047 datasets." (PMID 34116676, 2021). "The TME in neuroblastoma has been extensively reviewed, pointing to roles for immune cells, non-immune cells, and MYCN amplification, influencing therapy response and survival." (PMID 34572875, 2021). "We found that DST was an independent prognostic factor in MYCN non-amplified pediatric neuroblastoma and highly expressed in MYCN non-amplified younger neuroblastoma patients." (PMID 34116676, 2021). "The differentially expressed genes in MYCN non-amplified younger neuroblastoma patients in GSE49710 and GSE85047 datasets were also identified." (PMID 34116676, 2021). "Protein expression analysis showed homogeneous levels of ZRF1 among a panel of different neuroblastoma cell lines, regardless of MYCN amplification status." (PMID 34638328, 2021). "We initially investigated the knockdown of STRAP by utilizing siRNA in two neuroblastoma cell lines, which are AS (MYCN non-amplified) and BE (MYCN amplified), and found that STRAP knockdown resulted in decreased proliferation." (PMID 34206917, 2021). "Using the integrated analysis of TARGET, GSE49710 and GSE85047 datasets, our results showed that MYCN non-amplified pediatric neuroblastoma was heterogeneous, comprised younger and older sub-groups." (PMID 34116676, 2021). "DST was an independent prognostic factor in MYCN non-amplified neuroblastoma patients and MYCN non-amplified neuroblastoma younger patients with higher DST expression levels had the best clinical overall survival." (PMID 34116676, 2021). "Comparable IC50 values for alectinib were observed among neuroblastoma cell lines, regardless of the MYCN amplification status of cells." (PMID 34591871, 2021). "We further validated these findings by stable expression of two different short hairpin RNAs (shRNAs) designed to target RBM39 in four different neuroblastoma models, all of which are MYC-driven as a result of either MYCN amplification (BE2C, KELLY, and SIMA) or C-MYC overexpression (SK-N-AS)." (PMID 34788094, 2021). "BCL-2 is expressed significantly higher in neuroblastoma cells compared with other solid cancer lines, whilst BCL-XL expression is reduced, consistent with their responsiveness to Venetoclax and Navitoclax when MYCN is amplified." (PMID 34581776, 2021). "A subset of neuroblastoma cell lines that express high levels of MYC or MYCN does not respond to treatment with retinoids." (PMID 34669465, 2021). "The expression level of pro-proliferative Ki67 and cyclin D1 (CCND1) genes, as well as of MYCN and Nestin (controlling neuroblastoma aggressiveness), did not undergo any significant change in cells, independent of either 2D or 3D condition." (PMID 33230715, 2021). "Attempting to decipher how MYCN expression escapes elevated expression of inhibitory miRNAs, we present evidence that RNA-binding proteins like the IGF2 mRNA binding protein 1 reduce miRNA-directed downregulation of MYCN in neuroblastoma." (PMID 34026620, 2021). "MCM10, MCM2, MCM3, and MCM6 are among the high-risk signature correlating with poor prognosis in both MYCN-amplified and MYCN-non-amplified neuroblastoma." (PMID 35056094, 2021). "Here, using TARGET, GSE49710 and GSE85047 datasets, the transcriptional profiling of MYCN non-amplified younger neuroblastoma patients was identified." (PMID 34116676, 2021). "MYCN non-amplified younger neuroblastoma patients with higher DST expression levels have the best clinical overall survival." (PMID 34116676, 2021).
neuroblastoma (continued). "Neuroblastomas were previously divided into five groups based on TMMs: TERTp rearrangement, MYCN amplification, TERT expression high, ALT, and no TMM41." (PMID 33420056, 2021). "In neuroblastoma PDX tissues, all MYCN-positive cells showed expression of VRK1." (PMID 33233777, 2020). "Amplification of MYCN or constitutive upregulation of MYC protein is observed in approximately half of high-risk tumors; TAMs play a role as inducers of MYC expression in neuroblastomas lacking independent oncogene activation." (PMID 32244473, 2020). "Recently, a Cre-conditional mouse model of neuroblastoma (LSL-MYCN;Dbh-iCre), and induces conditional expression of MYCN in dopamine β-hydroxylase-expressing cells through Cre recombination and carries ~75% incidence of spontaneous tumor development regardless of strain background." (PMID 32983125, 2020). "Neuroblastomas with enhanced expression of N-MYC without MYCN amplification are known to be similarly high-risk and poor prognosis." (PMID 33614505, 2020). "We then depleted PRMT1 in two independent MYCN-non-amplified neuroblastoma cell lines SK-N-AS and SH-EP1, and observed similar suppression of cell proliferation in both cell lines." (PMID 32415090, 2020). "Likewise, blockade of essential amino acid transport triggers the GCN2‐eIF2α‐ATF4 pathway and inhibits neuroblastoma tumor growth, which is concomitant with attenuated translation of MYC and MYCN mRNAs." (PMID 32310340, 2020). "VRK1 expression is also significantly higher in MYCN-amplified versus nonamplified neuroblastoma tumors." (PMID 33233777, 2020). "MYCN (V-myc myelocytomatosis viral-related oncogene, neuroblastoma derived) amplification, associated with spontaneous NB and found in about 20% of all NBs, is associated with a poor prognosis; although children with tumors without MYCN amplification can also do poorly." (PMID 32726962, 2020). "We calculated the fold changes (FC) of miRNA expression between MYCN-amplified and non-amplified neuroblastoma samples after applying different normalization schemes." (PMID 32993488, 2020). "We therefore focused our analysis on 12 cell lines lacking MYCN amplifications but expressing MYCN at different levels, allowing for the identification of MYCN-driving enhancers in neuroblastoma." (PMID 33199677, 2020). "Due to high GPC2 expression in neuroblastomas with 7q gain and diploid MYCN, GPC2 was not one of the genes to be differentially overexpressed when comparing MYCN amplified to non-amplified tumors." (PMID 32211329, 2020). "Next, we created cell plugs from both MYCN amplified and non-amplified neuroblastoma cell lines and performed immunocytochemistry for CAMKV." (PMID 32211329, 2020). "The mRNA levels of TG2 isoforms, hypoxia-inducible factor (HIF)-1α, p16, cyclin D1 and B1, as well as markers of cell proliferation/death, DNA damage, and cell cycle were examined in SH-SY5Y (non-MYCN-amplified) and IMR-32 (MYCN-amplified) neuroblastoma cells in hypoxia/reoxygenation conditions." (PMID 32085516, 2020). "It is present at diagnosis and is never acquired during later tumorigenesis of MYCN non-amplified neuroblastoma." (PMID 33585251, 2020). "In addition, chemoresistant gene signature predicts outcome independently of current prognostic factors, including age at diagnosis, International Neuroblastoma Staging System (INSS) stage, and MYCN status in both datasets." (PMID 32948088, 2020). "Our current study demonstrated that PLK1 was highly expressed in neuroblastoma cells, and its expression level was independent of the MYCN status." (PMID 32231733, 2020).
neuroblastoma (continued). "A functional MYCN/c-MYC signature also characterizes a fraction of aggressive NB without MYCN amplification, which suggests that increased MYC activity is a main driver of aggressiveness in neuroblastoma." (PMID 32309213, 2020). "Studies on neuroblastoma have found that high CHD5 expression is closely related to favorable clinical and biologic characteristics, while low expression or deletion is related to adverse characteristics such as MYCN amplification and poor prognosis." (PMID 33062682, 2020). "Expression signatures correlated with differences in patient outcomes for MYCN non-amplified neuroblastoma, osteosarcoma, and synovial sarcoma." (PMID 32275708, 2020). "The zebrafish model showed that MYCN induced neuroblastoma does not develop from the earliest cells populating the superior cervical ganglia." (PMID 33585251, 2020). "Study also confirmed that MYCN and SOX2 were involved in the mechanism of neuroblastoma formation." (PMID 32857725, 2020). "Mitotic kinases, such as Aurora kinase A (AURKA) and Polo-like kinase 1 (PLK1), are reported to stabilize MYCN by inhibiting the Fbxw7-mediated degradation of the MYCN protein and may promote SCD in MYCN-amplified neuroblastoma cells." (PMID 33194665, 2020). "In GSE85047 dataset, neuroblastoma patients without MYCN amplification were divided into EIF4G1 highly expressed group and EIF4G1 lowly expressed group." (PMID 32593299, 2020). "Conversely, MYCN KD was found to downregulate MDM2 in IMR-32 neuroblastoma cells but not in NB-1691 and NB-1643 neuroblastoma or RB176 retinoblastoma cells, implying that MYCN dependent MDM2 expression is cell line-specific." (PMID 33425720, 2020). "Nevertheless, these results support the notion that the PRMT1-ATF5 axis plays a critical role in neuroblastoma cell growth and survival, regardless of MYCN amplification status." (PMID 32415090, 2020). "Here, we propose mitotic kinase Mps1 as a target for neuroblastoma cells regardless of MYCN copy number status." (PMID 32686724, 2020). "The upregulation of Twist-1 correlates with MYCN-amplification in neuroblastoma indicating that apoptosis evading mechanisms are different in MYCN amplified compared to non-amplified neuroblastoma." (PMID 33585251, 2020). "Our SILAC proteomics analysis revealed over-expression of HSP90 in MYCN-amplified IMR-32 compared to the non-MYCN amplified SK-N-SH human neuroblastoma cells, rendering them highly resistant to therapeutic intervention." (PMID 33569349, 2020). "Areal forward scatter measured experimentally by flow cytometry for control high-MYCN, MYCN-inhibited and rapamycin-treated (40 nM) TET21N neuroblastoma cells; shown are two biological replicates, indicated by solid and dashed lines, that were measured with the same FACS settings." (PMID 31971512, 2020). "Analysis of neuroblastoma patients showed that Mps1 expression was significantly higher in MYCN amplified neuroblastoma compared to non-amplified." (PMID 32686724, 2020). "VRK1 expression was variable among the cell lines and does not seem to correlate with MYCN amplification, but the kinase was expressed in all neuroblastoma cell lines and PDX samples tested." (PMID 33233777, 2020). "MYCN, an MYC family proto-oncogene, is amplified in 25% of neuroblastomas." (PMID 31920463, 2020). "The age, International Neuroblastoma Staging System (INSS) stage, MYCN gene amplification, DNA ploidy, histology, MKI (mitosis karyorrhexis index), and Children Oncology Group (COG) risk score were commonly used as prognostic indexes in clinic for evaluating NBL severity." (PMID 33044945, 2020). "Although MYCN amplification is a major indicator of poor prognosis in neuroblastoma, the efficacy of YM155 was independent of the MYCN status." (PMID 32131402, 2020).
neuroblastoma (continued). "When considering the distribution of polygenic risk scores across and between groups, there was little evidence that the MYCN‐amplified neuroblastoma patients were enriched for extreme outlier polygenic scores that would skew analyses." (PMID 32945147, 2020). "While our findings show that PBK lies downstream of both LIN28B and MYCN, and the functions of PBK mimic those of LIN28B in vitro, whether PBK sculpts neuroblastoma metastasis in the in vivo setting is unknown." (PMID 32923517, 2020). "Knocking down ATRX decreased colony formation in MYCN-amplified neuroblastoma cells (IMR32 and NB-5) but not cell lines expressing wild-type MYCN." (PMID 32060267, 2020). "TumorMap analysis showed that the MYCN-non-amplified (MYCN-NA) neuroblastoma samples clustered separately from MYCN-amplified (MYCN-A) and stage 4S neuroblastoma samples." (PMID 32275708, 2020). "Moreover, we found that PLAGL2 knockdown induced neuroblastoma cell differentiation and reduced cell proliferation, and combined knockdown of PLAGL2 and MYCN showed a synergistic effect." (PMID 32087738, 2020). "Yamashiro’s group found that suppression of ATF5 activity with an inhibitory peptide led to a concentration-dependent decrease of cell viability and increase of cell apoptosis in a panel of human neuroblastoma cell lines regardless of MYCN amplification." (PMID 32415090, 2020). "Anyhow, it is RNA N6-methyladenosine modification, but not the mRNA or protein MYCN expression level alone is important in miR-98/MYCN axis-mediated inhibition of neuroblastoma progression." (PMID 32788584, 2020). "In neuroblastoma, patients with high levels of GRHL1 expression show favorable prognosis, consistent with the suppressed tumor growth phenotype seen in the xenografts carrying forced GRHL1 expression in MYCN-amplified neuroblastoma cells." (PMID 32974388, 2020). "CUX2 is a direct MYCN target and is upregulated in MYCN-amplified neuroblastomas but not ATRX-mutant neuroblastomas." (PMID 32060267, 2020). "In our experiments, MYCN regulation by 13-cisRA was not attenuated by repeated exposure to the drug in neuroblastoma cells, but escape from sustained suppression of MYCN occurred via MYC transcriptional activation." (PMID 32409685, 2020). "Knockdown of CDK2 or treatment with the CDK2 inhibitor roscovitine induces apoptosis in MYCN-amplified neuroblastoma cell lines but not in those with MYCN single copy." (PMID 33628735, 2020). "The previous reports suggested that miR-542-3p was downregulated in favorable histology, MYCN non-amplified neuroblastoma." (PMID 33987474, 2020). "We deployed the ESTIMATE algorithm to figure the immune/stromal/ESTIMATE scores of neuroblastoma cases and found these scores were not correlated with age/chromosome 11q, but tumor stage, MYCN gene amplifications, and chromosome 1p." (PMID 32963529, 2020). "While we had intended to nominate candidate immunotherapy targets for MYCN amplified neuroblastoma that lacked normal tissue expression, the analysis did not yield any targets." (PMID 32211329, 2020). "Furthermore, as TH-MYCN tumors are driven by MYCN amplification it is worth noting that this model may not be appropriate for investigating the biology of MYCN non-amplified high risk neuroblastoma." (PMID 33028899, 2020). "We found that neuroblastoma patients without MYCN amplification and with low EIF4G1 expression had best prognosis." (PMID 32593299, 2020). "Here, we present chromatin immunoprecipitation sequencing (ChIP-Seq) data for the oncogenic transcription factors, MYCN and MYC, as well as regulatory histone marks H3K4me1, H3K4me3, H3K27Ac, and H3K27me3 in ten commonly used human neuroblastoma-derived cell line models." (PMID 32286315, 2020).